PKNOX2 (PBX/knotted 1 homeobox 2)
Synonyms: PREP2
Tractability: PROTAC: ubiquitination databases record sites on it.
Gene: Protein-coding gene on chromosome 11 (125,164,537 to 125,434,287, forward strand). Ensembl gene ENSG00000165495.
Subcellular location: Nucleus
Subcellular location (Human Protein Atlas): Nucleoplasm; Cytokinetic bridge
Gene Ontology:
Molecular function: protein binding; sequence-specific double-stranded DNA binding; DNA-binding transcription factor activity; RNA polymerase II cis-regulatory region sequence-specific DNA binding; actin filament binding; actin monomer binding; DNA binding; RNA polymerase II transcription regulatory region sequence-specific DNA binding; sequence-specific DNA binding
Biological process: positive regulation of transcription by RNA polymerase II; regulation of DNA-templated transcription
Cellular component: nucleoplasm; actin cytoskeleton; cytoplasm; microtubule cytoskeleton; nucleus
Genetic constraint (gnomAD): Loss-of-function variants: 14 observed, 56.01 expected, observed/expected ratio (o/e) 0.25, 90% interval 0.16 to 0.39. The upper end of that interval is the gene's LOEUF score, 0.39, which puts it in group 1 of 6, group 1 being the genes least tolerant of losing a copy. Missense variants: 496 observed, 626.31 expected, observed/expected ratio (o/e) 0.79, 90% interval 0.74 to 0.85. Synonymous variants: 257 observed, 253.58 expected, observed/expected ratio (o/e) 1.01, 90% interval 0.92 to 1.12.
Homologues: Orthologues: chimpanzee PKNOX2 (100% identical), macaque PKNOX2 (99% identical), rabbit PKNOX2 (99% identical), pig PKNOX2 (99% identical), dog PKNOX2 (99% identical), mouse Pknox2 (99% identical), guinea pig PKNOX2 (99% identical), rat Pknox2 (99% identical), tropical clawed frog pknox2 (90% identical), zebrafish pknox2 (78% identical), Drosophila melanogaster hth (30% identical), Caenorhabditis elegans unc-62 (28% identical), and 5 more. Paralogues in human: PKNOX1 (57% identical), MEIS2 (35% identical), MEIS1 (33% identical), MEIS3 (31% identical), MEIS3P2 (28% identical), PBX1 (18% identical), PBX3 (18% identical), PBX2 (16% identical), PBX4 (15% identical), TGIF1 (12% identical), TGIF2LX (10% identical), TGIF2 (10% identical), and 1 more.
Diseases named in the same sentence as PKNOX2 in open-access papers:
PKNOX2 is named in the same sentence as 18 diseases in open-access papers, as found by Europe PMC text mining. Sharing a sentence is not in itself a finding about the gene and the disease. The quoted sentences say what the papers report.
alcohol addiction (2 papers, 2011 to 2020). "Genome-wide associated studies revealed that PKNOX2 is associated with alcohol addiction in mice and humans." (PMID 32023328, 2020). "The nuclear transcription factor PKNOX2 has been previously identified as one of the cis-regulated genes for alcohol addiction in mice." (PMID 21298047, 2011). "Later, PKNOX2 was identified as one of the cis-regulated genes for alcohol addiction in mice." (PMID 21298047, 2011).
dependence (2 papers, 2011 to 2012). "We have found a novel, genomewide significant association of a composite substance dependence phenotype with a SNP in the PKNOX2 gene in White women." (PMID 21298047, 2011). "Associations of the 8 most significant SNPs in PKNOX2 with six individual substance dependence outcomes (p-values)." (PMID 21298047, 2011). "Summary of the 8 most significant SNPs in PKNOX2 gene showing genomewide significant association with substance dependence in White women." (PMID 21298047, 2011). "In this report, we present a genomewide significant association (α = 0.05) of PKNOX2 gene on chromosome 11 with composite substance dependence in European-origin women." (PMID 21298047, 2011). "Thus our findings make an important contribution in reporting PKNOX2 as a novel candidate gene for substance dependence in humans, particularly for White women in the SAGE sample." (PMID 21298047, 2011). "Thus we present PKNOX2 as a novel candidate gene for substance dependence in humans." (PMID 21298047, 2011). "However, PKNOX2 has not been reported to be associated with any substance dependence phenotype in humans to date." (PMID 21298047, 2011). "The identification of PKNOX2 as a candidate gene for substance use disorders underscores two important issues: (a) this has not been possible in the past due to limited sample size; and (b) we have considered a composite trait of six substance dependence outcomes as a whole." (PMID 21298047, 2011).
gastric cancer (2 papers, 2019 to 2022). A primary or metastatic malignant neoplasm involving the stomach. "Promoter methylation of PKNOX2 was associated with poor survival in gastric cancer patients." (PMID 30745575, 2019). "Using genome-wide methylation array, we first identified PBX/Knotted Homeobox 2 (PKNOX2) as a candidate tumor suppressor in gastric cancer." (PMID 30745575, 2019). "PKNOX2 mRNA expression is largely silenced in gastric cancer cell lines and primary gastric cancer via promoter methylation." (PMID 30745575, 2019). "PKNOX2 is able to upregulate IGFBP5 transcription in gastric cancer cells." (PMID 36093095, 2022). "Being a pro-apoptotic and anti-mitogenic protein, PKNOX2 acts tumor-suppressive on gastric cancer." (PMID 36093095, 2022). "PKNOX2 promoter hypermethylation might be a biomarker for the poor survival of gastric cancer patients." (PMID 30745575, 2019). "Notable targets up-regulated by PKNOX2 include BTG2, a tumor suppressor with anti-proliferative and anti-metastatic properties, and RPRM, which has been reported to suppress tumorigenesis in gastric cancer." (PMID 30745575, 2019).
lung carcinoma (2 papers, 2022 to 2023). "However, MYBL2 is only co-expressed in lung cancer microarray CCP, TBX4 is only co-expressed in lung cancer RNA-Seq CCP, PKNOX2 is not co-expressed in any CCP, and neither is a regulator in the GRNs." (PMID 36661515, 2023).
ovarian carcinoma (2 papers, 2023 to 2025). A malignant neoplasm originating from the surface ovarian epithelium. "Deletions in the PKNOX2 gene region are linked to breast cancer and ovarian cancer malignancies." (PMID 41149035, 2025). "LINC02489 interacts with PKNOX2 through the PTEN/mTOR axis to reduce the migration and invasion of chemotherapy-resistant SKOV3 cells, thereby increasing the sensitivity of ovarian cancer to paclitaxel." (PMID 37047747, 2023).
substance abuse (2 papers, 2016 to 2017). The use of a drug for a reason other than which it was intended or in a manner or in quantities other than directed. "PKNOX2, which regulates the transcription of other genes and affects anatomical development, has been linked to various types of substance abuse in European women." (PMID 28361705, 2017). "Interestingly, the PKNOX2 gene, a Homeobox-Containing Gene expressed highly in the brain, has been previously associated with substance abuse and formal thought disorder in SZ." (PMID 27276213, 2016).
dilated cardiomyopathy (1 paper, 2024). Cardiomyopathy which is characterized by dilation and contractile dysfunction of the left and right ventricles. "Considering that bulk gene profiling might conceal the changes in PKNOX2 in individual cells, we explored fibroblast remodelling in transplanted failing hearts with dilated cardiomyopathy (DCM, n = 3) in comparison to healthy controls (n = 3) with optimized snRNA-seq." (PMID 38644381, 2024).
heart failure (1 paper, 2024). Inability of the heart to pump blood at an adequate rate to meet tissue metabolic requirements. "The expression of genes related to fibrosis and heart failure was also obviously downregulated in AAV9-Postn-Pknox2-GFP mice." (PMID 38644381, 2024). "The expression of genes and proteins related to fibrosis and heart failure was also obviously upregulated in Pknox2-KO mice." (PMID 38644381, 2024). "Nevertheless, the in vivo study using the murine TAC model demonstrated a convincing therapeutic effect of enhancing PKNOX2 on alleviating myocardial fibrosis and cardiac dysfunction, indicating a novel potential antifibrotic target in heart failure remodelling." (PMID 38644381, 2024). "Collectively, these results demonstrated that PKNOX2 plays an essential inhibitory role in pathological myocardial fibrosis and might be a potential therapeutic target in myocardial remodelling during heart failure." (PMID 38644381, 2024). "Furthermore, to study the function of these TFs in maintaining homeostasis with a focus on myocardial fibrosis remodelling, a heart failure model was used in which we identified PKNOX2 as an essential regulator in myocardial fibrosis remodelling." (PMID 38644381, 2024). "Moreover, fibroblast-specific overexpression and knockout of PKNOX2 in a heart failure mouse model induced by transverse aortic constriction surgery significantly improved and aggravated myocardial fibrosis, respectively." (PMID 38644381, 2024). "To confirm the effect of PKNOX2 in pathological myocardial fibrosis, we generated fibroblast-specific PKNOX2 knockout mice (AAV9-Col1a2-Cre&PKNOX2 flox; Pknox2 CKO) and induced a heart failure model through transverse aortic constriction (TAC) operation." (PMID 38644381, 2024).
male infertility (1 paper, 2022). The inability of the male to effect fertilization of an ovum after a specified period of unprotected intercourse. "Among the other validated hits were proteins involved in the ubiquitin proteasome system (STAMBP and MYLIP), transcription (MTA1, PKNOX2), translation (EIF4E3), male infertility (RABL2A, DAZAP1), and virus-induced oncogenesis (MTA1)." (PMID 35452674, 2022).
Myocardial fibrosis (1 paper, 2024). "The in vivo study confirmed the therapeutic effect of enhancing PKNOX2 on alleviating myocardial fibrosis and cardiac dysfunction." (PMID 38644381, 2024).
schizophrenia (1 paper, 2023). A major psychotic disorder characterized by abnormalities in the perception or expression of reality. "PKNOX2 has also been identified as a candidate gene for schizophrenia in two large studies." (PMID 37861717, 2023).
tumor (7 papers, 2011 to 2025). "qPCR analysis of tumours from each group revealed that Pknox2, Irf4, Pou3f1, Cebpb, and Meox1 were significantly upregulated by propionate and B. fragilis." (PMID 40715695, 2025). "Research on PKNOX2 has focused on its roles in diseases, such as inhibition of tumor cell migration, proliferation by PKNOX2 promoter demethylation, and induction of apoptosis." (PMID 37047747, 2023). "PKNOX2 overexpression significantly suppresed tumor growth and reduced tumor weight at the end point (both P < 0.001)." (PMID 30745575, 2019). "The up-regulated genes were associated with apoptosis induction (BTG2, TP73 and PIDD1) and cell cycle arrest (RPRM and CDNK1A), consistent with the tumor suppressive function of PKNOX2." (PMID 30745575, 2019). "Tumor size was significantly smaller in PKNOX2 overexpression group than that in control group (P < 0.001)." (PMID 30745575, 2019). "A series of in vitro and in vivo functional studies revealed that PKNOX2 functions as a tumor suppressor." (PMID 30745575, 2019). "Cell proliferation in the tumor tissues from nude mice was evaluated by Ki-67 immunostaining assay, and the PKNOX2 group displayed decreased cell proliferation compared to control group (P < 0.01)." (PMID 30745575, 2019). "We revealed that PKNOX2 possesses tumor suppressive effects in GC cells and inhibits GC growth by inducing cell apoptosis and cell cycle arrest, and inhibiting metastasis in vitro and in vivo." (PMID 30745575, 2019). "PKNOX2 has also been found to be expressed in melanoma, but was silenced in human tumor cell lines from various tissues." (PMID 30745575, 2019). "IGFBP5 knockdown partly abrogated tumor suppressive effect of PKNOX2, indicating that the function(s) of PKNOX2 are dependent on IGFBP5." (PMID 30745575, 2019). "IGFBP5 thus operates as a tumor suppressor in GC cells expressing PKNOX2." (PMID 30745575, 2019). "PKNOX2 exerted tumor suppressive effects by inhibiting cell proliferation, migration and invasion." (PMID 30745575, 2019). "PKNOX2 promoter hypermethylation is associated with poor outcomes in GC patients, suggesting that PKNOX2 could function as a tumor suppressor in GC." (PMID 30745575, 2019). "Besides, the average tumor weight in PKNOX2 overexpression group was significantly reduced compared to control group (P < 0.05)." (PMID 30745575, 2019). "Ectopic PKNOX2 expression inhibited cell proliferation in GC cell lines and suppressed growth of tumor xenografts in mice via induction of apoptosis and cell cycle arrest; and suppressed cell migration and invasion by blocking epithelial-to-mesenchymal transition." (PMID 30745575, 2019). "Collectively, these results indicate that PKNOX2 functions as a tumor suppressor in GC." (PMID 30745575, 2019).
tumor (continued). "In summary, our study indicated for the first time that PKNOX2 functions as a candidate tumor suppressor in GC by induction of apoptosis, inhibition of cell cycle progression and blockade of EMT, culminating in inhibition of cell growth, migration/invasion in vitro and tumorigenicity in vivo." (PMID 30745575, 2019). "Based on these findings, we hypothesized that tumor suppressive effect of PKNOX2 in GC might be mediated by IGFBP5." (PMID 30745575, 2019). "We next assess if IGFBP5 has a tumor suppressive role in GES1 cells that express endogenous PKNOX2." (PMID 30745575, 2019). "Collectively, these findings indicate that PKNOX2 suppresses tumor growth in GC." (PMID 30745575, 2019). "Ectopic expression of PKNOX2 in tumor tissues from nude mice was confirmed by RT-PCR." (PMID 30745575, 2019). "Hence, PKNOX2 inhibits GC cell proliferation, suggesting that it functions as a tumor suppressor." (PMID 30745575, 2019). "PKNOX2 positively regulates IGFBP5 expression in vitro and in vivo by acting as a tumor suppressor." (PMID 36465383, 2022). "Moreover, cell viability and colony formation assays revealed that IGFBP5 silencing abrogated the tumor suppressive effect of PKNOX2 in AGS cells overexpressing PKNOX2, suggesting that tumor suppressive function of PKNOX2 in GC cells was dependent on IGFBP5." (PMID 30745575, 2019). "In addition, three genes common to both patients which carried bivalent marks in normal and lost H3K4me3 in tumor, LHX9, PKNOX2 and LBXCOR1 and one, PRDM8, lost the H3K27me3 in tumor, all of which are transcription factors with unknown function in colon." (PMID 22011431, 2011).
cancer (3 papers, 2019 to 2024). A tumor composed of atypical neoplastic, often pleomorphic cells that invade other tissues. "Other upregulated target genes include the Homeobox TF genes PRRX1 and PKNOX2, both of which have roles in mesenchyme development, while PRRX1 also promotes EMT in cancers." (PMID 35904801, 2022).
infection (1 paper, 2024). The state of being infected such as from the introduction of a foreign agent such as serum, vaccine, antigenic substance or organism. "Furthermore, a gain-of-function experiment was conducted by overexpressing Pknox2 using adenovirus-delivered plasmid (adv-PKNOX2) infection in AMCFs." (PMID 38644381, 2024).
PKNOX2 also shares sentences with these, for which no sentence is quoted: alcohol dependence (1 paper); breast carcinoma (1); cocaine dependence (1); opiate dependence (1).